CALR (calreticulin)
Diseases named in the same sentence as CALR in open-access papers (continued):
Sharing a sentence is not in itself a finding about the gene and the disease.
tumor (continued). "In the dying tumor cell, ICD is preceded by the translocation of calreticulin, an endoplasmic reticulum stress response protein, to the plasma membrane and the extracellular release of ATP and the high-mobility group box-1 (HMGB1) protein." (PMID 32781554, 2020). "Three specific molecules appear to be required for optimal immune priming against malignant cells: the membrane localization of calreticulin, and the release of HMBG1 and ATP into the tumor microenvironment." (PMID 31731707, 2019). "Extracellular calreticulin (CRT) and release of HMGB1 are two important DAMPs required for the induction of immunogenic cell death, responsible for inducing an effective anti-tumor immune response." (PMID 32642649, 2019). "Here, calreticulin acts as an “eat me signal”, further enhancing the tumor cell phagocytosis by DCs and the consequent expansion of CD8+T-cells with anti-tumor activity." (PMID 31117237, 2019). "This was associated with the activation of endoplasmic reticulum stress and tumor cell death with features of immunogenic cell death (ICD), including phosphorylation of eIF2α, increased cell surface calreticulin levels, and release of HMGB1 and ATP." (PMID 31641103, 2019). "Both calreticulin and HMGB1 were found to be essential for the antigen-specific T-cell responses in murine tumor models." (PMID 30941308, 2019). "Necrotic tumor cells can release immune-stimulatory proteins, such as calreticulin (CRT), heat shock protein (HSP) and tumor-specific antigens." (PMID 31554195, 2019). "Radiotherapy can lead to the release of tumor antigens and/or DAMPs, such as calreticulin, HMGB1, or ATP, which can activate both the innate and adaptive immune system, and enhance tumor-cell immunogenicity." (PMID 29482595, 2018). "Particularly, allogeneic tumor cell lysates obtained from heat shocked conditioned tumor cells contain elevated levels of danger signals (like released HMGB1 and translocated calreticulin), which improve DC maturation and tumor antigen cross-presentation." (PMID 29499656, 2018). "Surface-exposed calreticulin is a crucial DAMP in ICD, as it dictates tumor specific immunity, allowing the recognition and engulfment of tumor cells by dendritic cells." (PMID 30080874, 2018). "In in vitro tumor cell models it has been shown that proton radiation, compared to photon radiation, resulted in a higher translocation of calreticulin thereby increasing the cross-priming of TAA and the sensitivity of the tumor cells to CTL-mediated killing." (PMID 30619273, 2018). "Calreticulin can interact with LDL-receptor-related protein 1 on macrophages and is required for the phagocytosis of tumor cell lines, whose function is to neutralize CD47–SIRPα interaction." (PMID 28484448, 2017). "It revealed that all these five targets (GSN, ADAMTSL4, CALR, PPIA and TXN) can be secreted by the NPC 6-10B and 5-8F cells, which provided an important basis for our following studies to identify the serum tumor biomarkers of NPC." (PMID 28107202, 2017). "In conclusion, our results collectively provided a potential biomarker dataset for NSCLC prognosis and revealed that CALR and PDIA3 were over-expressed in NSCLC compared with adjacent non-tumor lung tissues." (PMID 29228584, 2017). "The over-expressions of CALR and PDIA3 in tumor tissues were confirmed by real-time PCR using 20 paired tissues, and verified by western blot analysis." (PMID 29228584, 2017). "Immunohistochemistry analysis of TMA displayed that CALR and PDIA3 were mainly localized in the membrane and cytoplasm of the tumor cells." (PMID 29228584, 2017). "LC-MS/MS-based quantitative analysis showed that CALR and PDIA3 were significantly up-regulated in NSCLC tissues relative to adjacent non-tumor lung tissues." (PMID 29228584, 2017). "The selected dysregulated proteins CALR and PDIA3 were found to be over-expressed in NSCLC compared with adjacent non-tumor lung tissues." (PMID 29228584, 2017).
tumor (continued). "While the link between calreticulin-TRAIL cognate interaction and iNKT-dependent tumor killing requires further corroborating research, it would potentially provide a molecular mechanism for the iNKT cell-mediated antitumor effects in a variety of cancers." (PMID 29326711, 2017). "Patient samples were subdivided by disease stage, stage II and stage III, and the ratio of calreticulin, calnexin, GRP78 and GRP94 in tumour versus normal tissue was evaluated." (PMID 27369741, 2016). "Calreticulin, ERp57, GRP78/BiP, Annexin1 and Tapaxin were downregulated in western blotting analysis of extracts from HCT116 tumours, whereas they were all upregulated in those with a silenced miR-27a." (PMID 26913609, 2016). "Consistently, calreticulin displayed a weak and mainly cytosolic positivity on sections of HCT116 tumours by IHC." (PMID 26913609, 2016). "Here, we extend previous findings by demonstrating molecular responses in patients with pre-PMF and PMF with high and intermediate initial mutant allele burdens indicating that IFN may induce molecular remissions regardless of the MPN diagnosis of CALR mutated patients and their initial tumor load." (PMID 27764253, 2016). "Gutiérrez and Simmen describe the conditions by which ER chaperones and oxidoreductases (calreticulin, ERp57, PDI, and GRP94) escape retention and enhance tumor elimination by the immune system." (PMID 26636034, 2015). "In this model, anthracyclins induced the translocation of calreticulin (CRT) to the cell surface, and CRT was exposed by dying tumor cells phagocytosed by DCs, resulting in the presentation of tumor antigens and the induction of immunogenicity in tumor cells." (PMID 24520271, 2014). "Some types of tumor cell deaths can induce a DC-mediated cytotoxic T lymphocyte (CTL) response, wherein calreticulin, a Ca2+ binding protein, becomes exposed on the cell surface during immunogenic cell death." (PMID 24434638, 2014). "The data on the urine and tumor tissues obtained from UTUC patients which were discovered and verified by proteomic and immunological analysis strongly suggested that CALR, annexin A2 and annexin A3 are essential proteins secreted from UTUC tumor tissues." (PMID 24884814, 2014). "Combined the experimental data in the urine and in tumor tissues collected from patients with UTUC, the crucial over-expressed proteins are calreticulin, annexin A2, and annexin A3." (PMID 24884814, 2014). "Side-by-side comparisons of CALR, ZAG, annexin A2, annexin A3 and Hp showed the different expression between tumor tissues and normal tissues." (PMID 24884814, 2014). "Ideally, an efficient therapy would aim to generate cell surface calreticulin to serve as an efficient “eat-me” signal on tumor cells, while down-regulating or inactivating BiP/GRP78 on the plasma membrane, which acts as tumor-promoting." (PMID 25386408, 2014). "Once at the plasma membrane, ER chaperones and oxidoreductases serve as DAMPs for the immune system (calreticulin, GRP94) or modulators of tumor hallmarks (BiP/GRP78, PDI)." (PMID 25386408, 2014). "Heat shock proteins, including calreticulin (CRT), HSP70, and gp96, have been shown to act as potent immunoadjuvants to enhance antigen-specific tumor immunity." (PMID 23533454, 2013). "In conclusion, wogonin can enhance the immunity of tumor cell vaccine, in which ER stress activated AKT signaling pathway mediated calreticulin/Annexin A1 translocation and/or HMGB1/ATP release are involved." (PMID 23251389, 2012). "The generation of an immunogenic tumor cell death through the induction of calreticulin, HSP, release of inflammatory mediators, proinflammatory cytokines or HMGB1 will favor the recognition of tumor cell antigens by DC, NK, and T cells." (PMID 19272170, 2009). "In addition, both γδ T and NK cells degranulated and consistently induced lysis in a panel of NB cell lines and patient-derived 3D tumor spheres expressing B7H6, calreticulin, HA-TAG, BTN2A1, and BTN3A1/2/3 consistently." (PMID 41694338, 2026).
tumor (continued). "Our pH-sensitive nanozyme enables tumor-specificGOx delivery, initiating glucose depletion and ROS accumulation, whichin turn promote ICD through the release of DAMPs such as ATP, HMGB1,and calreticulin." (PMID 41493269, 2026). "As tumor cells undergo death following BNCT treatment, they release a series of signaling molecules, such as surface-exposed calreticulin (CRT), secreted ATP, and extracellular HMGB1, which trigger adaptive immune response; this mode of cell death is known as immunogenic cell death (ICD)." (PMID 41179690, 2025). "Radiotherapy can trigger the abscopal effect through immunogenic cell death, releasing tumor antigens and danger signals such as HMGB1 and calreticulin, which activate dendritic cells and prime cytotoxic CD8+ T cells via the cGAS–STING/type I interferon pathway." (PMID 41300968, 2025). "Importantly, HIF-1α can interact with the Wnt/β-catenin signaling pathway through the transcriptional upregulation of calreticulin (CALR), thereby enhancing tumor development." (PMID 41373022, 2025). "This bidirectional regulation manifests in two ways: on one hand, ERS induces ICD through calreticulin exposure, HMGB1 release, and ATP secretion, enhancing anti-tumor immunity; on the other hand, it promotes immune suppression via mechanisms such as PD-L1 glycosylation." (PMID 41407677, 2025). "Calreticulin, ATP, and HMGB1 bind to CD91, P2RX7, and TLR4, respectively, facilitating dendritic cell (DC) recruitment into the tumor bed (by ATP), the phagocytosis of tumor antigens by DCs (enhanced by CRT), and an optimal antigen presentation to T cells (stimulated by calreticulin and HMGB1)." (PMID 40313247, 2025). "RT-induced tumor cell DNA breaks leading to the genomic instability that triggers tumor cell apoptosis, the release of high mobility group box 1 protein (HMGB1) and ATP, and the translocation of calreticulin on the tumor cell surface (eat-me signal)." (PMID 40141437, 2025). "The dying cancer cells release damage-associated molecular patterns (DAMPs), such as high mobility group box 1 (HMGB1) and calreticulin (CRT), into the tumor microenvironment, promoting dendritic cell maturation and recruiting immune cells for the amplification of ICD." (PMID 40797208, 2025). "Key in vivo endpoints will include tumor growth inhibition and tumor rechallenge studies, animal survival, and spatial distribution of ICD markers (e.g., HSP‐70, calreticulin, HMGB1) and tumor‐infiltrating CD8+ T cells with respect to V‐LNP distribution and incident light propagation in tumors." (PMID 41256215, 2025). "CALR and ATP (an ICD marker) secretion were both increased in ACADS-OE tumours (P < 0.05)." (PMID 39800718, 2025). "Moreover, GEPIA data indicated that PRC1 had a positive expression correlation with ICD markers, including CD274 (PD-L1), CALR (CRT), and HMGB1 in tumor tissues from COAD and READ patients." (PMID 40847353, 2025). "Especially, immunofluorescence analysis demonstrated that HAQ/223Ra@HNPs treatment markedly increased the expression of ER stress-related proteins (CHOP, GRP78, and PERK) and ICD markers (CALR and HMGB1), accompanied by a significant upregulation of PD-L1 in tumor tissues." (PMID 41320759, 2025). "On the other hand, some of them can induce immunogenic cell death (ICD), inducing exposing calreticulin (CRT), releasing damage-related molecular pattern (DAMP) tumor antigens such as high-mobility group box 1 protein (HMGB1), and enhancing tumor immunogenicity." (PMID 38594751, 2024). "Calreticulin of O. viverrini (Ov CALR) is important for parasite fecundity and modulates the host immune system by binding with the C1q polypeptide of the complement system, affecting its role in inflammation and tumor cell attacks." (PMID 39050853, 2024). "Moreover, both calreticulin released during ICD and CD47 blockade can accelerate phagocytosis of tumor cells by macrophages, promote antigen presentation, and eventually induce T lymphocyte-mediated antitumor immunity." (PMID 38560565, 2024).
tumor (continued). "Calreticulin (CRT) engagement with CD91 fosters the maturation and activation of DCs, culminating in the cross-presentation of tumor antigens and the elicitation of tumor-specific cytotoxic T lymphocyte (CTL) responses." (PMID 38887519, 2024). "Ablative UTMC was employed to explore immunogenic cell death in a TNBC model (4T1, immune excluded with low TMB); UTMC induced the translocation and expression of calreticulin and enhanced IL-12 and TNF-α, leading to increased infiltration of DC and CTL in both the tumor and TDLNs." (PMID 38543305, 2024). "Following treatment, calreticulin exposure on the cell membrane peaked at 6 h, and the levels of ATP and HMGB1 increased significantly, indicating that combination therapy induces immunogenic cell death, thereby inhibiting tumor recurrence and metastasis." (PMID 39735534, 2024). "ICPs, such as PD-L1 and TIM-341,42, and ICD modulators, such as CALR and HMGB143–45, significantly regulate host anti-tumor immunity, influencing the effectiveness of mRNA vaccinations, showing that there is an important relationship between ferroptosis and immune regulation." (PMID 38331967, 2024). "The expression of CALR by CD163+ macrophages is seen in the tumor area, but not in the adjacent brain." (PMID 38786045, 2024). "This was likely because high-calreticulin tumor cells often appeared unspecifically in random control tumor regions independent of panobinostat efficacy." (PMID 36672243, 2023). "In addition, STING pathway‐activation‐mediated IFN secretion can alter tumor immunogenicity by upregulating PD‐L1, IDO, MHC I and calreticulin in tumor cells." (PMID 37560754, 2023). "Our analysis highlights that ASCETIC consistently identifies alterations in CALR, JAK2, and IDH1/2 genes as early events in tumor history, while NRAS represents an acquired secondary event, towards which evolutionary trajectories appear to converge during the progression of the disease." (PMID 37749078, 2023). "In addition to tumor-suppressing proteins that were enriched in CW-MSC CM such as CALR, we identified PCOLCE as a novel tumor-suppressing protein and proposed a regulatory axis of PCOLCE-APP for the treatment of OS." (PMID 36943734, 2023). "Consequently, extracellular HMGB1 along with JQ1-induced release of calreticulin (CALR), and ATP will provoke immunogenic apoptosis of tumor cells." (PMID 37511951, 2023). "DAMPs include calreticulin (CRT), Hsp70, ATP, HMGB1, etc., the appearance of which on the surface of dying cells or in the tumor microenvironment help determine whether cell death is immunogenic." (PMID 38131639, 2023). "To investigate whether the low-dose SNAP-mediated antitumor effect was correlated with ICD, we isolated tumor cells from LL2 tumor-bearing mice through CD326 magnetic beads and measured levels of the ICD marker, surface calreticulin." (PMID 36639681, 2023). "Similar to our results, the calreticulin expression on tumor cells was not essential in the process." (PMID 36672243, 2023). "In addition to the three substances (CALR, HMGB1, ATP), interleukin-12 (IL-12), a potent anti-cancer cytokine, is also important in the induction of anti-tumor immunity by OVs." (PMID 36293504, 2022). "Specifically, when the nanodrugs disrupt the ER, ER stress induces imbalances in calcium homeostasis, and calreticulin (CRT) transfers from the ER to the cell membrane to act as an “eat-me” signal, inducing inflammatory cell infiltration and enhancing tumor cell antigens presented." (PMID 35903337, 2022). "This study systematically evaluated the prognostic value of CALR expression in patients with KIRC using The Cancer Genome Atlas (TCGA) database, Clinical Proteomics Tumor Analysis Consortium (CPTAC), the Human Protein Atlas (HPA), Tumor Immune Estimation Resource (TIMER), and TIMER2.0." (PMID 36338983, 2022).
tumor (continued). "And then, we analyzed the relationship between CALR expression and the clinical features, and we found that high expression of CALR correlated with GC patients’ TNM stage, distant metastasis, histological differentiation, and tumor size." (PMID 35641480, 2022). "In fact, the release of DAMPs, including the eat-me signal calreticulin, may be necessary in addition to CD47 surface depletion to induce phagocytosis by macrophages, and may allow the discrimination of tumor cells from healthy cells." (PMID 35565443, 2022). "However, except for expression of PD-1 by CD45− cells in the contralateral (untreated) tumor, GSNO administered i.t. appeared to exert negligible effects on expression of tumor immunogenicity markers including calreticulin (CRT), CTLA-4, PD-1, and PD-L1." (PMID 35304456, 2022). "Unfortunately, blocking CD47‐SIRPα is not enough when the pro‐phagocytic molecule calreticulin (CALR) on tumor cells is low." (PMID 37323705, 2022). "The release of CALR, ATP, and HMGB1 molecules by dying cancer cells occurs within hours, a slow increase in T cells begins after 100 h, which peaks at 200 h, and the tumor cells are eliminated in about 220 h when a rapid increase in cytotoxic T lymphocyte cell population begins." (PMID 37420422, 2022). "Considered “eat me signals”, Hsp70 and calreticulin can interact with a variety of APC surface receptors, such as CD91 and CD40, to promote the cross-presentation of antigens on MHC class I molecules, thus triggering a tumor-specific CD8+ T-cell response." (PMID 36225934, 2022). "Additionally, signals for anti-tumor immunity like adenosine triphosphate (ATP), nuclear protein high-mobility group box-1 (HMGB1) and calreticulin (CALR) are produced upon ICD." (PMID 35432376, 2022). "Calreticulin, HSP70 and HSP90 are translocated to the cell surfaces of stressed or dying tumor human cells, where they interact with antigen-presenting cells and induce cell maturation and the activation of a “danger” response characterized by the production of proinflammatory cytokines." (PMID 33530324, 2021). "Previous studies demonstrated that both ICPs (e.g., PD-L1 and TIM-3) and immunogenic cell death (ICD) modulators (e.g., CALR and HMGB1) play critical roles in modulating the host anti-tumor immunity, which could influence the efficacy of mRNA vaccine." (PMID 33685460, 2021). "Independent of the pathological tumor stage, high calreticulin levels were more often observed in tumor specimens of neoadjuvant treated patients (N = 33) compared to tumor specimens of treatment-naïve pancreatic cancer patients (N = 18)." (PMID 33920544, 2021). "One day post treatment with AI, IP, AP, or ICB, the number of apoptotic tumor cells was doubled compared with untreated tumors, but tumor cell death was increased 3-fold following treatment with AIP, and these cells exposed calreticulin that promotes phagocytosis." (PMID 34818534, 2021). "However, some tumour cells overexpress stanniocalcin 1 (STC1), which obstructs calreticulin exposure on the cell surface, reducing phagocytosis of the cancer cells." (PMID 34177884, 2021). "Calreticulin (CALR) is a antigen characteristic of immunogenic cell death in non-small cell lung cancer (NSCLC), which is closely related to anti-tumor immunity, but its specific mechanism in anti-tumor immunity remains unclear." (PMID 34660305, 2021). "This hypothesis is supported by previous results such as increased calreticulin (CRT) exposure after TMZ treatment in GL261 cells and histopathological studies showing an increase in microglia/macrophage in responding tumours after TMZ standard treatment." (PMID 33233585, 2020). "Fhit-transfected B11 tumor cells had increased transcriptional levels of the following genes: Fhit, H-2 class I heavy chains, β2-microglobulin, Tap-1, Tap2, LMP2, LMP10, Tapasin, calreticulin, Erap1, ERp57, PA28α, Ttp1, and Ttp2." (PMID 32545680, 2020).